GRM1 (glutamate metabotropic receptor 1)
Diseases named in the same sentence as GRM1 in open-access papers (continued):
Sharing a sentence is not in itself a finding about the gene and the disease.
ductal carcinomas (1 paper, 2013). "The cumulative incidence of ductal carcinomas by age of diagnosis was evaluated for associations with GRM1 genotypes." (PMID 23922822, 2013). "For GRM1 rs6923492, ER+/PR+ ductal carcinomas in TT carriers occurred at a later age as compared to either TC or CC carriers, corresponding to the right shift in the curve." (PMID 23922822, 2013).
prion disease (1 paper, 2021). A transmissible disease that is caused by a protein that is able to induce abnormal folding of normal cellular proteins, leading to characteristic spongiform brain changes, which are associated with neuronal loss without an inflammatory response. "Analysis of activity-related neuronal receptors which are involved in development of LTP and LTD, such as Grm1 and Grin2a, showed a decrease in response to ME7 prion disease and were significantly lower following systemic exposure to S. typhimurium." (PMID 35058740, 2021).
prostate tumor (1 paper, 2014). "Exome sequencing of 112 prostate tumor/normal pairs identified two missense mutations (A573E and R681H) in GRM1 gene." (PMID 25062106, 2014). "Genotype status of mutations and SNPs identified in GRM1 gene in matched prostate tumor-normal tissues." (PMID 25062106, 2014). "Sequencing of selected exons-8 and -9 of GRM1 gene in prostate tumor tissues showed multiple genetic alterations." (PMID 25062106, 2014).
type 1 diabetes (1 paper, 2019). "Variants in the metabotropic glutamate receptor group I pathway, including GRM1 and GRM5, were enriched in the pathway analysis of a recent albuminuria GWAS among people with type 1 diabetes from the FinnDiane study (no individuals overlapped with the current gene-aggregate meta-analysis)." (PMID 30547231, 2019).
urinary tract infection (1 paper, 2021). "Indeed, GRM1 and GRM2 can be found in the majority of bacterial species associated with urinary tract infections." (PMID 34054778, 2021).
uveal melanoma (1 paper, 2018). A melanoma derived from melanocytes of the uveal tract. "As the Grm1 transgene is placed under control of the melanocyte specific Dct promoter, Grm1 is specifically overexpressed in cells of melanocytic origin leading to both cutaneous and uveal melanoma." (PMID 29535818, 2018).
tumor (62 papers, 2010 to 2025). "Additionally, analyses of the clonogenic potential revealed an increased ability to form colonies from single cells of both primary tumor and metastatic Cyld-deficient Tg(Grm1) cells compared to Cyld+/+ cells." (PMID 31591386, 2019). "Comparing the tumor progression of AP2ε-/-/Tg(GRM1) and Tg(GRM1)-mice we observed significant induction of local tumor progression for the tail (G first panel), perianal region (second panel), and ear (third panel) in the AP2ε deficient mice." (PMID 38773108, 2024). "Tumor genome sequencing data have indicated that GRM1 is one of the pivotal driving genes for CRC stage II progression." (PMID 38706895, 2024). "Consistent decreases in phospho-forms of ERK and AKT in tumor tissue analyses with accompanying decrease in GRM1 expression and increase in pro-apoptotic BIM suggest target engagement by the combination." (PMID 37036756, 2023). "The tumour cells were diffusely positive for smooth muscle actin and GRM1 (in > 95% of the neoplastic cells), focally positive for CD34 and negative for S100 protein, desmin, cytokeratin AE1AE3 and ERG." (PMID 36810795, 2023). "The importance of Grm1 on tumor growth in vivo was supported by the decrease in growth induced by Grm1 knock-down in xenografted cells." (PMID 35158973, 2022). "Introduction of Grm1 cDNA into immortalized primary baby mouse kidney (iBMK) cells resulted in cellular transformation in vitro and tumor formation in vivo." (PMID 34359771, 2021). "Homozygous mice which harbor two copies of the disrupted Grm1 gene display raised pigmented lesions by four to six weeks and succumb to high tumor burden by four months of age." (PMID 34359771, 2021). "Introduction of Grm1 cDNA into iMMECs induced cellular transformation in vitro and tumor formation in vivo with enhanced tumor angiogenesis." (PMID 34359771, 2021). "In line with this, the DC boost approach is able to partially control tumor growth in the tg(Grm1)EPv mouse model." (PMID 33408092, 2021). "In the absence of xCT, the glutamate release-inhibitory activity of riluzole is much reduced, which is reflected as a decrease of riluzole-mediated anti-proliferative task in GRM1-expressing tumor cells." (PMID 30425240, 2018). "Hypoxia, as a common feature of tumour microenvironment, increases the transcription of glutamate receptors, promotes the activation of GRM1, 3, 4, and 5, and supports proliferation and survival of several types of tumours through MAPK and PI3K/Akt SPs31,107." (PMID 29062084, 2017). "In contrast, introduction of exogenous GRM1 into melan-A cells resulted in cell transformation in vitro and robust tumor formation in vivo." (PMID 27941674, 2016). "GRM1 is expressed in many cancer cell types as compared to normal counterparts underscoring its potential role in tumor behavior." (PMID 23922822, 2013). "Characterization of the intracellular signals evoked as a consequence of GRM1 activation provides the basis for its molecular role in oncogenesis and tumor progression." (PMID 23922822, 2013). "Exercise significantly inhibits tumour development and growth in preclinical models of hot tumours including transplanted Lewis lung cancer, diethylnitrosamine induced liver cancer and melanoma (GrM1) mouse models." (PMID 38149260, 2023). "Moreover, the DC boost approach equips not only the migratory cDC1 but also the migratory cDC2 in the tumor-draining LNs of the tg(Grm1)EPv mouse model with the ability to prime gp100-specific CD8+ T cells." (PMID 33408092, 2021). "We suspect that if mutated BRaf is expressed first, then a critical but unknown pathway is also activated, preventing Grm1 -induced neoplasia." (PMID 29464040, 2018). "Our earlier studies showed that genetic modulation in GRM1 expression by siRNA or disruption of GRM1-mediated glutamate signaling interfere with downstream effectors resulting in a decrease in both cell proliferation in vitro and tumor progression in vivo." (PMID 29416686, 2018).
tumor (continued). "However, the mice in our experiments were followed up to 8 months of age and the Grm1/SELENOK–/– mice continued to exhibit lower levels of tumor formation compared to Grm1/SELENOK+/+ and Grm1/SELENOK+/– littermates for both sexes." (PMID 29568366, 2018). "SELENOK-deficiency in Grm1-Tg/SELENOK−/− male and female mice inhibited primary tumor growth on tails and ears and reduced metastasis to draining lymph nodes down to levels equivalent to non-tumor control mice." (PMID 29568366, 2018). "Unlike mutated BRaf, aberrant Grm1 expression in melanocytes is sufficient to induce cell transformation in vitro and robust tumor formation in vivo with no alteration in p15 expression and almost undetectable TGFβ." (PMID 29464040, 2018). "Also consistent with primary tumor data, SELENOK deficiency in the Grm1-Tg mice led to a reduction of Trp2-positive cells in the lymph nodes at levels similar to mice lacking tumors (C57BL/6J and SELENOK–/– controls)." (PMID 29568366, 2018). "The metabolism of aggressive cancers may be altered by the presence of glutamate receptor 1 (GRM1) antagonists with subsequent development of the Warburg effect in the case of tumor-related induced hypoxia." (PMID 24396452, 2014). "GRM1 is a gene normally expressed and functional in the CNS, however, when GRM1 is ectopically expressed in mouse or human melanocytes, one of the consequences is cellular transformation in vitro and tumor formation in vivo." (PMID 24619402, 2010). "To overcome these limitations, we screened full-length GRM1 gene including all exons, exon-intron junctions, and flanking non-coding 5′- and 3′-untranslated regions (UTRs) to identify genetic alterations in several PCa cell lines and matched tumor-normal tissues in AAs and Caucasian Americans (CAs)." (PMID 25062106, 2014). "The expression of mGluR1 (GRM1) and mGluR5 (GRM5) was conserved from primary tumours to metastatic samples, but moderate changes were evident for other receptors such as mGluR2/3/7/8 (GRM2, GRM3, GRM7, and GRM8)." (PMID 37173906, 2023). "We report a purely subcutaneous CMF harbouring a novel PNISR::GRM1 gene fusion, adding CMF in the differential diagnosis of tumours arising in superficial soft tissues." (PMID 36810795, 2023). "Glutamate metabotropic receptor 1 (GRM1) and retinoblastoma 1 (RB1) were additional alterations found in PDX15, for the patient normal, tumor, and PDX tumor tissue." (PMID 32825052, 2020). "We demonstrated that aberrant expression of metabotropic glutamate receptor 1 (GRM1) in melanocytes was sufficient to induce cell transformation and metastatic tumor formation in vitro and in vivo." (PMID 30425240, 2018). "Immunohistochemically, the tumour cells were diffusely positive for smooth muscle actin and GRM1, and negative for S100 protein, desmin and cytokeratin AE1AE3." (PMID 36810795, 2023). "In addition to a radiologic and clinical response, this patient displayed statistically significant decreases in GRM1, AKT, and pro-apoptotic protein BIM in analyses of paired tumor tissue, supporting target engagement and activity." (PMID 37036756, 2023). "This analysis revealed that the metastatic Tg(Grm1) Cyld−/− cells show a reduced doubling time in comparison to Cyld-expressing cells, whereas the proliferative potential from primary tumor cells with or without CYLD expression was comparable." (PMID 31591386, 2019). "Both, primary tumor and metastatic Tg(Grm1) Cyld−/− cells display significantly increased migration compared to the cell lines derived from Tg(Grm1) Cyld+/+mice, whereas cell attachment was not influenced by CYLD." (PMID 31591386, 2019). "To test whether mGluR1 can regulate PMN migration into tumors, we used the GRM1-expressing 4T1 mouse tumor model to measure PMN presence in the tumors after injections with riluzole or sunitinib, an anti-angiogenic drug known to regulate PMN migration." (PMID 30375476, 2018).
tumor (continued). "Recently we also showed that in an in vivo mouse model with conditioned mutated BRAF (V600E), GRM1 expression is detected after mutated BRAF expression is activated, however, no tumor was detected in these mice up to 17 months of age." (PMID 27941674, 2016). "Thus, we treated tg(Grm1)EPv mice at the transition between the TE and the TA stages with a mAb against PD-L1 but this treatment was not sufficient to delay tumor growth." (PMID 33408092, 2021). "Given the observed association between activation of GRM1 with that of CK1, it is postulated that the role of CK1 as a tumor suppressor may be mediated by a negative feedback loop with GRM1." (PMID 23922822, 2013).
cancer (31 papers, 2010 to 2025). A tumor composed of atypical neoplastic, often pleomorphic cells that invade other tissues. "As metastasis is the main cause of death for cancer patients, and since AP2ε is upregulated in the migratory phenotype, we next investigated the impact of AP2ε loss on metastasis in the Tg(GRM1) mouse model." (PMID 38773108, 2024). "Given the role of these pathways in cancers, we speculated that GRM1, GRM2 and GRM7 may be associated with DIPG progression by involving in these pathways." (PMID 30124166, 2018). "Although multiple mutations have been reported in GRM1 gene in different human cancers, only a limited number of high-throughput studies including whole exome sequencing or transcriptome analysis were carried out and identified few GRM1 mutations in PCa samples." (PMID 25062106, 2014). "In addition to overexpression, mutations and single nucleotide polymorphisms or SNPs of GRM1 have been identified in multiple cancers, such as prostate, colorectal, and lung, that led to alterations in receptor activation, intracellular localization, and downstream signaling." (PMID 36457557, 2022). "Therefore, the multifaceted role of GRM1 in cancer biology positions it as a promising target for the development of targeted therapies aimed at disrupting key oncogenic processes." (PMID 41424711, 2025). "Moreover, several later studies conducted in different cancer models supported these findings when they detected a more than threefold increase in extracellular glutamate from GRM1 expressing cells compared with controls." (PMID 32937954, 2020). "Cancer stem cell pools were also decreased in Grm1-Tg/SELENOK−/− mice compared to littermates." (PMID 29568366, 2018). "The aggressiveness and malignancy exhibited by cancers aberrantly expressing GPCRs, such as GRM1, may be due to the release of exosomes that are functionally more aggressive." (PMID 29416686, 2018). "Finally, transduction of MCF10AT1 cells, which express c-Ha-ras, using a lentiviral construct expressing GRM1 results in transformation to carcinoma in 90% of resultant xenografts." (PMID 24404125, 2014). "Cancer cell lines have also been observed to secrete its ligand glutamate extracellularly where it may act in an autocrine or paracrine manner to activate GRM1." (PMID 23922822, 2013).
infection (9 papers, 2014 to 2025). The state of being infected such as from the introduction of a foreign agent such as serum, vaccine, antigenic substance or organism. "We inspected the expression of the Grm1 protein during the infection of brain cells and confirmed the downregulation of this protein illustrating the long-term effects of T. gondii infection on the glutamatergic synapse." (PMID 34610266, 2021). "According to Western and QPCR analysis, ten days after infection, both mGluR1 protein levels and GRM1 message were inhibited in all shGRM1-infected cells compared to NS vector-treated cells." (PMID 24633367, 2014).
neurological diseases (9 papers, 2011 to 2024). "In LHQW, arctiin, corymbosin, and aloe-emodin target neurological disease-related genes (GRM1 and GRM5), whereas in QFPD, isofucosterol, baicalein, nobiletin, oroxylin A, epiberberine, and piperlonguminine target immunity- and inflammation-related genes (mTOR and PLA2G4A)." (PMID 36210820, 2022).
psychiatric disorder (7 papers, 2010 to 2025). A disorder characterized by behavioral and/or psychological abnormalities, often accompanied by physical symptoms. "The significant modulations of Grm1 and Slc39a12 at the proteomic level also support the biomolecular connection of bilirubin-induced damage with neuro-behavioral/psychiatric disorders that could manifest in youth and adult age." (PMID 40650037, 2025).
CNS tumors (1 paper, 2019). "The natural ligand of GRM1 is L-glutamate; the CNS is a glutamate rich environment, thus making the study of glutamate signaling in CNS tumors an interesting and rational area for testing new hypotheses." (PMID 31073373, 2019).
prostate (1 paper, 2014). "Functional validation of these mutations will further strengthen the role of genetic alterations of GRM1 gene in prostate carcinogenesis and progression." (PMID 25062106, 2014).
GRM1 also shares sentences with these, for which no sentence is quoted: Ataxia (28 papers); encephalitis (15); Cognitive impairment (9); Arthritis (6); autoimmune encephalitis (6); cerebellar degeneration (6); Alzheimer disease (5); Hodgkins lymphoma (5); ischemia (5); autoimmune disorder (4); bipolar disorder (4); Huntington disease (4); Intellectual disability (4); multiple sclerosis (4); alcoholism (3); lymphoma (3); myasthenia gravis (3); neuromyelitis optica (3); paraneoplastic cerebellar degeneration (3); Parkinson disease (3); renal cell carcinoma (3); scrapie (3); autism spectrum disorder (2); autoimmune disease (2); Autosomal Recessive Spinocerebellar Ataxia (2); brain ischemia (2); dementia with Lewy bodies (2); epileptic encephalopathies (2); glioblastoma (2); ischemic stroke (2).
A further 87 diseases each share a sentence with GRM1 in 2 papers or fewer.